IL6 (interleukin 6)
Diseases named in the same sentence as IL6 in open-access papers (continued):
Sharing a sentence is not in itself a finding about the gene and the disease.
tumor (continued). "Experiments in vitro demonstrated that IL-6 enhanced PD-L1 expression in the tumor tissue through the JAK1/Stat3 pathway, leading to immune evasion." (PMID 37833968, 2023). "The lipolysis cascade activation in peritumoral adipocytes is also promoted by tumor-derived IL-6 via the AMPK pathway signaling that increases the adipose triglyceride lipase (ATGL) and the free fatty acid (FFAs) release in the TME." (PMID 37760840, 2023). "In the present study, Rh4 led to the inactivation of IL-6/STAT3 signaling in LPS-stimulated HCC cells and in the tissues of mouse HCC subcutaneous transplanted tumor, evidenced by reduced IL-6 and p-STAT3 expression." (PMID 37843550, 2023). "Specifically, the overexpression of NOTCH family members through modulation of IL-6 signaling in vitro results in the acquisition of aggressive tumor cell features, such as a higher proliferation rate and independence from IL-6." (PMID 37834003, 2023). "Even though IL-6 can be harnessed to manipulate the tumor microenvironment and enhance the body’s immune response, its suppressive effects on standard systemic treatments significantly overshadow the potential benefits of elevated IL-6 levels." (PMID 37892997, 2023). "Tumor cells and stromal cells further promote the generation and expansion of Th17 cells by secreting IL-1, IL-6, IL-23, and TGF-β." (PMID 37680632, 2023). "Tumor cells themselves produce a variety of inflammatory factors and chemokines to recruit TAMs including IL-6, IL-8, and IL-34." (PMID 38138294, 2023). "There was a significant difference in IL-6 levels between patients with tumor resectability of suboptimal resection > 1 cm vs optimal resection < 1 cm (1328 vs 752 pg/ml; p<0,001)." (PMID 37792745, 2023). "Platelets release IL-6 and also trigger IL-6 secretion from tumor cells by releasing several factors, such as lysophosphatidic acid (LPA)." (PMID 36831623, 2023). "IL-6 is a major player in chronic inflammatory diseases, autoimmune diseases, cancer, and tumor immunity." (PMID 36835413, 2023). "Recently, we revealed that ARG1 was activated in murine bone marrow-derived dendritic cells and human monocyte-derived dendritic cells to suppress the induction of anti-tumor effector T cells in an IL-6-dependent manner." (PMID 36639644, 2023). "Macrophages activate STAT3 in tumor cells by expressing IL-6, thereby enhancing the proliferation and survival of malignant cells even during chemotherapeutic treatment." (PMID 36757936, 2023). "While IL-6 predominantly promotes tumor growth and advancement, it also exhibits a paradoxical impact in specific scenarios, showcasing the contrasting influences of this cytokine." (PMID 37892997, 2023). "An in vivo study reported that the IL-6 released by MSCs led to an increase in the levels of endothelin-1 secreted in tumor cells, involving endothelial cell activation via the Akt/ERK signaling pathway promoting angiogenesis." (PMID 37686315, 2023). "Conditioned tumor cell medium treated with 10 μM 5-aza showed upregulation of 4 key cytokines—IL-6, IP-10 (CXCL10), KC (CXCL1), and RANTES (CCL5)—which activate both adaptive and innate immune responses." (PMID 37627156, 2023). "Jia and co-authors found that MSCs express iNOS, CCL2, IL-6, and Cox-2 and recruit macrophages at tumor sites." (PMID 37686315, 2023). "The overexpression of SUMO2 increased IL6 production by T cells, which are potent killers of tumor cells." (PMID 37123398, 2023). "Kupffer cells, or resident hepatic macrophages, are considered tumour-associated macrophages of HCC and can produce a variety of cytokines, most notably interleukin (IL)-6, a pro-inflammatory marker, to promote HCC tumorigenesis." (PMID 36901717, 2023). "Both TNF-α and IL-6 have been shown to be classical indicators of macrophage activation and in vivo demonstrated to mediate tumor promotion in various human cancers." (PMID 37784035, 2023).
tumor (continued). "Among the cytokines tested, the most significant indicators of tumour progression in ALK + NSCLC were IL-6, IL-8 and IL-10." (PMID 37120670, 2023). "Conversely, in macrophages-HOS and macrophages-143B co-cultures, the IL-10/IL-6 ratio increased after mifamurtide administration both in macrophages and in tumor cells." (PMID 37835437, 2023). "It is well documented that the presence of cytokines such as IL-1, IL-6, and TNF-α or chemokines such as CCL2 and CXL8 from white blood cells or tumor-associated macrophage (TAMs) generate cancer-related inflammation in tumors." (PMID 36900505, 2023). "In this context, it has been observed in several types of malignancies, including HR-NB, that high levels of IL-6 and the soluble form of its receptor (sIL-6R) in the patient’s blood and BM, correlated with bad prognosis and would support tumor growth." (PMID 36980226, 2023). "TLR2, TLR4, and inflammasome inducing MR, NLRP3 can lead to tumor progression via the production of inflammatory cytokines (IL6, IL16), increased cell proliferation, and resistance to apoptosis (TNFAIP3)." (PMID 37599366, 2023). "As let-7 miRNAs are mainly expressed in bulk tumor cells but not breast CSCs, we propose that XIST-driven IL-6 production from ALDH− bulk tumor cells plays a major role in maintaining ALDH+ CSCs via paracrine IL-6 signaling." (PMID 36922677, 2023). "In this study, the authors show that LECs residing in the lymph nodes and lungs are conditioned by tumor-secreted IL-6 to express and secrete CCL5 in a p-STAT3-HIF-1α-VEGF-dependent manner, creating an inflammatory PMN for metastasizing cells." (PMID 37887354, 2023). "Genes associated with a pro-inflammatory tumour microenvironment included TNF, IL6, IL18, NLRP3, IL1B and CASP1 which were also comparable between sporadic and NF2-SWN VS samples." (PMID 37680691, 2023). "Researchers used anti-IL-6 antibody and CSF-1R inhibitors to block the monocytes recruitment into tumor tissue; others by decreasing the population of TAMs, such as anti-CD11b antibody." (PMID 36969873, 2023). "Tumoral cells can express suppressor cytokines (IL-6, IL-10, TFGβ, TNFα), which promote tumor growth and metastasis, suppressor cells (LT reg), and immunosuppressive molecules." (PMID 36830015, 2023). "During the burn-induced inflammatory response, pro-inflammatory cytokines such as IL-6, IL-8, tumor TNF-α, and anti-inflammatory cytokines such as IL-10 are released." (PMID 37090725, 2023). "On the other hand, CCA tumor cells augment IL6 production in vCAFs through the secretion of exosomes containing miR-9-5p to form a regulatory loop between tumor cells and vCAFs." (PMID 36980203, 2023). "Our discovery of high levels of the pro-inflammatory cytokines TNFα, IL-1β, and IL-6 led us to test if these cytokines aided in tumor destruction or promotion." (PMID 37461742, 2023). "Research has shown that exercise can reduce the levels of inflammatory factors (such as TNF-α, IL-6, IL-1β) and reactive oxygen species (ROS) within tumor tissue, thus inhibiting the inflammatory immune microenvironment in tumors." (PMID 37691942, 2023). "In HCC, tumor cells secrete a large amount of TGFβ, while CAFs produce relatively lower levels of TGFβ, IL-6 and granulocyte-colony-stimulating factor (GCSF) to promote N2 neutrophils." (PMID 36835352, 2023). "The fact that GPR68 is able to increase IL-6 expression is important since IL-6 plays a fundamental role in tumor progression." (PMID 36902589, 2023). "When it comes to angiogenesis, IL-6 propels the development of fresh blood vessels within the tumor (angiogenesis), furnishing crucial nutrients and oxygen to sustain tumor growth and enlargement." (PMID 37892997, 2023). "We observed that IL‐6 was secreted specifically by both CD8+ and CD4+ CAR T cells in response to stimulation through the CAR by tumor cells expressing the EGFRvIII mutation." (PMID 36890859, 2023).
tumor (continued). "Tumor-derived cytokines such as IL-6 and IL-27 have promoted PD-L1+CD8+ T cells development through STAT1/STAT3 signaling." (PMID 37077914, 2023). "Bulk tumor samples were stimulated ex vivo with cytokines with defined roles in antitumor immunity (interleukin-2 [IL-2], IL-6, and interferon-α [IFN-α])." (PMID 37192001, 2023). "While often critical for the immune response to pathogens, pro-inflammatory cytokines (TNFα, IL-1β, and IL-6) play mixed roles in tumor pathogenesis." (PMID 37461742, 2023). "Although IL-6 produced from ALDH− bulk tumor cells promotes ALDH+ CSCs in a paracrine fashion, downregulation of IL-6 and upregulation of let-7a-2-3p expression, despite to a lesser extent, were also detected in ALDH+ CSCs upon XIST KD." (PMID 36922677, 2023). "TNF stimulates T-cell extravasation on tumor vessels and IL6 trans-signaling enhances T-cell transmigration on tumor vessels." (PMID 37069585, 2023). "Exploring CM content revealed the enrichment of a number of soluble factors in the tumor-activated HS-5, such as soluble uPAR (SuPAR), IL-6, and hepatocyte growth factor (HGF)." (PMID 37175439, 2023). "LGALS3 plays a role in apoptosis and cell adhesion, and stimulates bone marrow mesenchymal stem cells to express interleukin-6 (IL-6) to promote tumorigenesis, inflammation of the tumor microenvironment, and metastasis." (PMID 36980828, 2023). "In TME, IL-6 promotes the proliferation and invasiveness of tumour cells and strongly inhibits anti-tumour immune responses." (PMID 37462801, 2023). "While the overall mechanisms responsible for the IL-6 increase within the CRC tumor stroma remain to be elucidated, our study highlights the crucial role of stromal vitamin A pathway in IL-6 regulation." (PMID 37185128, 2023). "Compared to untreated M-MØ, cGAMP induced higher STING activation and higher levels of IL-6 and IFNβ1 in MTX-M-MØ, thus indicating that MTX also alters macrophages-responses to a danger-associated stimulus commonly present in the tumor microenvironment." (PMID 36380627, 2023). "Innate immune cells, such as M1 macrophages, tumor associated granulocytes, and classical monocytes, are known to exert anti-tumor effects with increased proinflammatory cytokines, including IL-1β, IL-6, and TNF-α, and reactive oxygen species." (PMID 38125025, 2023). "Studies have shown that conventional chemotherapy alters the tumor immune landscape, while IL-6 and G-CSF induce neutrophil infiltration, modulate effector T cells and promote tumor progression." (PMID 37699010, 2023). "IL-6 is produced by the tumor cells themselves or by different tumor-infiltrating immune cells or stromal cells." (PMID 36672405, 2023). "Specifically, Sphingomab targeted endothelial cells from the tumor microenvironment inhibiting the release of proangiogenic factors (IL-6, IL-8, VEGF) and therefore reducing tumor vascularization." (PMID 37345069, 2023). "Although it is widely known that CAFs are central players in shaping the TME toward immunosuppression by mediating the immune system, we focused on the IL-6-mediated recruitment of tumor-infiltrating immune cells by CAFs and their fate in a hypoxic TME." (PMID 36764954, 2023). "For example, Platelet derived growth factor (PDGF) and TGF-β produced by tumor cells were shown to induce fibroblasts activation, and activated fibroblasts secrete IL-6 to promote tumor cell proliferation and chemotherapy resistance." (PMID 37978384, 2023). "In a different study, it was reported that reduced pericyte coverage increased IL-6 expression in the hypoxic tumor microenvironment and MDSC transmigration and circulating malignant cell phenotype." (PMID 37056346, 2023). "Increased levels of VEGF improve vascularity in the tumor tissue, while IL-6 promotes an inflammatory environment that is known to facilitate tumor growth." (PMID 36851555, 2023). "This suggested that the main role that TNFα, IL-1β, IL-6 played in the tumor was exerted by and on macrophages." (PMID 37461742, 2023).
tumor (continued). "Omeprazole and pantoprazole have been already proved to decrease pro‐inflammatory factors such as TNF and IL‐6, and increase anti‐inflammatory factors such as IL‐10 implying the potential for anti‐tumour." (PMID 35961680, 2023). "After the gap junction is established, endothelial cells receive IL-6 and IL-8 from tumor cells and secrete endothelin to tumor cells both through the paracrine pathway, resulting in an increased expression of survival protein in tumor cells." (PMID 37056723, 2023). "For example, the myokine interleukin 6, released by skeletal muscle, is a natural killer cell in tumor surveillance." (PMID 36263581, 2023). "Among the list of cytokines, IL-6, IL-17, M-CSF, and tumor antigen, LPS are essential for stimulating transcriptional activators responsible for inflammasome assembly and autophagy activation." (PMID 37893079, 2023). "Reciprocally, the subsequent release of inflammatory cytokines (IL-6, TNF-α, TGFβ and CXCL12) from CAFs causes EMT and a pro-metastatic switch of CRC cells, and it also facilitates tumor formation and lung metastasis." (PMID 36831450, 2023). "Another KRAS/STK11 mouse model study established tumor regression following T cell infiltration subsequent to IL-6 antibody administration, while the same models were irresponsive to PD-1 mAb." (PMID 36899885, 2023). "Surprisingly, the promoting effect of cSERPINE2 overexpression on tumor growth and metastasis was blocked by anti-IL-6 antibody." (PMID 36797769, 2023). "Immunostaining of the resected tissue showed IL-6 focal positivity, which meant the phenotype of tumor cells focally changed their phenotypes over time." (PMID 37908215, 2023). "Collectively, these data suggest that targeting IL-6, IL-8, and their receptors is a promising approach to inhibiting tumor metastasis and cancer lethality." (PMID 38187701, 2023). "As Interleukin 6 (IL-6) can both prevent and encourage the anti-tumour immune response, it is difficult to ascertain the benefits of its potential decrease by PSD for PDAC." (PMID 37627163, 2023). "An anti-IL-6 antibody slows tumor growth by increasing CD8+ T-cell infiltration and decreasing Tregs presence." (PMID 37520562, 2023). "IL-6/STAT3 signaling promotes tumor cell proliferation, metastasis, angiogenesis, immune suppression, cancer stemness and chemotherapeutic resistance." (PMID 36614179, 2023). "IL6 secreted by MSCs in TME promotes cancer progression supporting increased tumor invasion, proliferation, and resistance to chemotherapy of cancer cells." (PMID 36661524, 2023). "Similar to previous studies, our study found that increased IL-6 secretion by tumor exosomal cSERPINE2-educated TAMs elevated the expression of CCL2 to enhance TAMs infiltration." (PMID 36797769, 2023). "High expression of IL‐6 was discovered in many tumour tissues and positively correlated to poor prognosis of cancer." (PMID 36419386, 2023). "Tumor necrosis factor-α (TNF-α), granulocyte colony-stimulating factor, interleukin-1 (IL-1), and IL-6 are produced by tumor cells and can induce a tumor-related systemic inflammatory reaction (SIR)." (PMID 36719281, 2023). "M2d macrophages, also known as tumor-associated macrophages (TAMs), are induced by adenosine A2 receptor (A2AR), leukemia inhibitory factor (LIF) and IL-6, and mainly inhibit inflammatory reaction and promote angiogenesis and tumor growth." (PMID 36903624, 2023). "It was discovered that IL-6 produced in the tumor microenvironment promotes the formation of metastatic lesions in CRC cells." (PMID 36639644, 2023). "For example, ZC3 has been shown to interact with several immune-related genes, including interleukin-6 and a large group of interferon-stimulated genes, which play a role in anti-tumor immune response." (PMID 38033582, 2023). "Unexpectedly, iCAF markers (CLEC3B and IL6) were largely and significantly upregulated in tumor tissues." (PMID 37444482, 2023).
tumor (continued). "We found that TNFA and IL6 expression was upregulated in SUM44 GR+ tumor cells, suggesting a possibly enhanced capacity to metastasize to the bone." (PMID 37835373, 2023). "M1-type macrophages can exert anti-tumor effects by producing active factors and pro-inflammatory cytokines such as interleukin 6 (IL-6), IL-12, and interferon-γ (IFN-γ) active." (PMID 37415241, 2023). "Numerous studies and several pioneer factors, such as EGFR, IL-6, TGFβ revealed that liver regeneration and tumor development are inseparable process." (PMID 37315292, 2023). "IL-6 and IL-6 receptors have roles in the growth and differentiation of tumor cells and in angiogenesis through the JAK (Janus kinase)-STAT signaling pathway." (PMID 37373987, 2023). "This study strongly supports a model in which XIST-driven IL-6 cytokine production from ALDH− bulk tumor cells promotes ALDH+ CSCs in a paracrine fashion." (PMID 36922677, 2023). "IL-6 has been identified as a cytokine that is significantly abundant within the tumor microenvironment (TME) across a spectrum of cancer types." (PMID 37892997, 2023). "IL-6, which is widely present in the tumor microenvironment, is a key gene involved in promoting tumor cell cycle progression and inhibiting apoptosis." (PMID 37081874, 2023). "It is considered that IL‐6 opposes tumor growth by mobilizing anti‐tumor T cell immune responses to attain tumor control." (PMID 36925700, 2023). "IL-6 is a pleiotropic cytokine secreted by many cells including lymphocytes, fibroblasts, monocytes/macrophages, and tumor cells." (PMID 37108657, 2023). "In particular, TNF-α and IL-6 have garnered considerable attention in the context of cancer, being labeled master regulators of tumor-related inflammation." (PMID 37964946, 2023). "We therefore analyzed the relationship between the levels of IL-6, IL-8 and IL-10 cytokines in the serum and tumor tissues, and the molecular subtypes of dogs with canine mammary gland tumors (CMGTs)." (PMID 36693957, 2023). "Many proteins impact CCL2 expression in tumor cells (e.g., inflammatory mediators such as interleukin-1, interleukin-6, tumor necrosis factor-alpha (TNFα) or transforming growth factor-β (TGFβ))." (PMID 37176074, 2023). "Conversely, it is known that IL-6 serum levels correlated with a poor prognosis, tumor burden, survival and progression in different cancers, thus being proposed as an anticancer therapeutic target." (PMID 36902351, 2023). "Simultaneously, the Se-PC peptide can enter the blood circulation, and irradiation promotes the synthesis of antioxidant enzymes and the immune response by the IL-6/TNF-α pathway to protect normal tissues against tumor metastasis." (PMID 37994159, 2023). "The combined effect of IL-6 on tumor growth can serve as a basis for targeted therapeutic interventions." (PMID 36873124, 2023). "For instance, the MAPK signaling pathway inhibits the activity of immune cells in the tumor microenvironment by up-regulating the release of IL-6/IL-10 and other cytokines." (PMID 36982415, 2023). "Previously, gankyrin was demonstrated to enhance hepatocarcinogenesis via STAT3 activation through SHP-1 inhibition and IL-6 upregulation in the tumor microenvironment." (PMID 36660927, 2023). "Studies have shown that senescent cells release SASP factors such as IL-6 and IL-8 into the tumor microenvironment, which can induce epithelial-mesenchymal transformation and thus play a role in promoting metastasis and invasion." (PMID 36950520, 2023). "At the same time, tumor-activated MSCs contribute to stem cell formation and migration potential of OS through secretion of IL-6." (PMID 37240338, 2023). "To further support these findings, we randomly selected subcutaneously transplanted tumor-bearing mice for IL-6 neutralization treatment." (PMID 36990991, 2023).